CCL2 (C-C motif chemokine ligand 2)
Diseases named in the same sentence as CCL2 in open-access papers (continued):
Sharing a sentence is not in itself a finding about the gene and the disease.
glioma (continued). "Moreover, overexpression of CCL2 is induced by upregulation of protein S100 calcium binding protein B, and this positive correlation between the two proteins promotes TAM recruitment in the glioma microenvironment." (PMID 30619286, 2018). "CCL2 production correlated with distinct CCR4+ Treg and CCR2+ myeloid derived suppressor cell (MDSC) populations infiltrating the tumor, suggesting these molecular steps may be largely responsible for the recruitment of immunosuppressive cell types in glioma." (PMID 32914058, 2018). "CCL2, a CC chemokine that stimulates CCR2, its corresponding receptor expressed on T cells, NK cells and γδ T cells, is reported to be expressed by various types of cancer cells including those of glioma, melanoma, and cancers of the breast, prostate, colon and lung." (PMID 23441216, 2013). "However, in order to understand the role of CCL2 in the specific extravasation of CD3+ lymphocytes, the correlation between the number of tumor infiltrating CD3+ T-cells and the number of expressing CCL2 cells in the glioma samples was calculated." (PMID 22319587, 2012). "Moreover, our mechanistic study identifies CCL2 as a potential downstream target of MEX3A, which possesses similar regulatory effects on glioma development with MEX3A and could attenuate the promotion of glioma induced by MEX3A overexpression." (PMID 33414423, 2021). "In conclusion, our findings suggest that downregulation of the CCL2/CCR2 and CXCL10/CXCR3 axes via inhibition of the NF-κB pathway in the tumor and the tumor microenvironment might have contributed to the antitumor effects of celecoxib observed in the mouse glioma model." (PMID 32943658, 2020). "However, given the previously discussed impact of Rab27a knockdown on CCL2 expression, this model may not be able to pin-point the exact mechanisms to study glioma–macrophage interactions via EVs." (PMID 33282910, 2020). "It is known that CCL2 and CCL7 are expressed by tumor and non-tumor cells within the glioma microenvironment." (PMID 36685592, 2022). "Moreover, the expression of Cd274 was well correlated with the respective expression of Ifng, Irf1, Gbp5, and Ccl2, demonstrating that selected IFN-γ-induced genes serve as feasible substitute indicators for IFN-γ level and thus might synergistically indicate the prognosis of glioma." (PMID 30333036, 2018). "However, the representative chemokines in glioma (CXCL12, CXCL16, CX3CL1, CCL2) were not significantly correlated with poor OS in the same database." (PMID 34638384, 2021). "Furthermore, an astonishingly high proportion of primary human glial tumors overexpress CCR2 (whilst normal brain structures do not), suggesting possibly a similar mechanistic bonding to CCL2." (PMID 21943176, 2011). "Importantly, a subset of these human-derived cytokines that included CXCL10, IL-33, CXCL8, KITLG, CCL2, and TGFα were not secreted or secreted at very low levels in vitro by BT147 cells, suggesting that the increased secretion was the result of a glioma–host cell interaction within the brain." (PMID 33020472, 2020).
melanoma (252 papers, 2005 to 2026). A malignant, usually aggressive tumor composed of atypical, neoplastic melanocytes. "The microphthalmia-associated transcription factor (MITF)-low melanoma, typically characterized by high stemness, produces a CCL2-rich secretome, which promotes the recruitment of TAMs." (PMID 40399946, 2025). "Increased and synergistic CCL2 expression and secretion have been demonstrated in dedifferentiated melanoma cells and linked to senescence induction in melanoma cells in vitro and myeloid cell recruitment in melanoma tumors in vivo." (PMID 39736644, 2024). "Little is known about the role of CCL2 in leukemia biology; however, high levels of CCL2 can be associated with a better prognosis in some tumor types such as melanoma and pancreatic cancer." (PMID 38731966, 2024). "In the present study, we provide evidence that the melanoma micromilieu enhances the production of CCL2, IL-8, IL-1β, and C3/C3a by MCs, factors associated with tumor progression." (PMID 35669782, 2022). "RT-qPCR assays demonstrated that Ccl2/Ccr2 and Cxcl9/Cxcl10/Cxcr3 levels were higher in B16 melanoma tumors from Cbx3/HP1γ-deficient mice than those from controls." (PMID 34721405, 2021). "CCL2 macrophage recruitment into melanoma was associated with higher-grade melanoma and promotion of tumor growth through increased TNF-α dependent vascularization." (PMID 30899263, 2019). "An analysis of their expression in a set of 39 melanoma cell lines confirmed their coordinated expression and the association with CCL2." (PMID 26684239, 2016). "The results showed that in association with CCL2 production, a set of coordinately regulated miRNAs is induced by BRAFi to control melanoma cell apoptosis." (PMID 26684239, 2016). "Senescence in melanoma cells is associated with production of a NF-κB-dependent secretome, which contains the chemokine CCL2." (PMID 24742694, 2014). "Inhibition of the MAPK activation pathway in Amela tumor lines led to reduced Smad3 signaling, affected expression of EMT hallmark genes and inhibited proinflammatory cytokine Ccl2 gene expression and production by the melanoma cells." (PMID 23173060, 2012). "Inhibition of the mitogen-activated protein kinase (MAPK) activation pathway in Amela tumor lines leads to reduced expression of EMT hallmark genes and inhibits both proinflammatory cytokine Ccl2 gene expression and Ccl2 production by the melanoma cells." (PMID 23173060, 2012). "A recent study reported that high systemic concentrations of CCL2 were positively associated with OS in melanoma patients with in transit metastasis treated with melphalan, possibly because of the capability of this chemokine to attract both T lymphocytes and monocytes within melanoma." (PMID 35173725, 2022). "These senescent cells develop a PARP-1 and NF-κB associated secretome (PNAS) containing chemokine CCL2 along with other SASP factors thereby augmenting the invasiveness of melanoma cells which might have escaped senescence." (PMID 33855023, 2021). "CCL2/CCR2 receptor ligand pair has been implicated in γδ T cell recruitment in B16 melanoma where they may exert a cytotoxic effect mediated by IFN-γ, perforin and granzyme B." (PMID 30899263, 2019). "The role of CCL2 production by melanoma cells remains somewhat controversial, as low CCL2 levels appear to attract tumor-associated macrophages, which promote tumor development, while high levels of CCL2 production attract macrophages that cause tumor regression." (PMID 22745913, 2012). "In a BRAFV600; PTEN KO mouse melanoma model in which eIF4E cannot be phosphorylated (eIF4EKI), they showed an increase in the secretion of many cytokines linked with the expansion, recruitment (such as CCL2, CCL12, and CCL5), and function (such as MMP-9) of immunosuppressive cells such as MDSCs." (PMID 35432344, 2022).
melanoma (continued). "Co-culture of melanoma cells with endothelial cells composing the abluminal surface of blood vessels, was demonstrated to induce the expression of genes linked to cancer cell migration (CCL2, ICAM1), cancer progression (TRAF1, SERPINB2) or stem cell properties (PDGFB; CFDP1)." (PMID 34604096, 2021). "Moreover, the brain microenvironment induces a loss of PTEN expression in metastatic melanoma cells, leading to an increased secretion of CCL2 and a subsequent recruitment of myeloid cells that enhance the outgrowth of brain metastatic melanoma cells via enhanced proliferation and reduced apoptosis." (PMID 33466236, 2021). "Recruited by macrophage chemo-attractants (i.e, CCL2, MCP1, CSF-1), tumor-associated macrophages represent up to 50% of tumor-infiltrating cells, as seen in melanoma, renal cancer, and colonic carcinoma, suggesting they may be able to efficiently infiltrate into solid tumors upon adoptive transfer." (PMID 33790906, 2021). "Melanoma lesions in elderly individuals often harbor fibroblast‐enriched desmoplastic zones and exhibit increased expression of chemokines such as CCL2 and CXCL12, which recruit suppressive macrophages and exclude effector lymphocytes." (PMID 40926366, 2025). "For example, elevated IL‐6 and CCL2 in BRAF‐inhibitor‐induced TIS models of melanoma correlated with increased infiltration of immunosuppressive macrophages, which dampened anti‐tumor T cell activity." (PMID 40926366, 2025). "More importantly, our data evidently supported a strong influence of E2F1 and its target IL-6 on the Th1/Th2 development like Th2 cytokine production, downregulation of ERK1/2 pathways, IFN-γ response (bottom), or CCL2 expression in melanoma cells." (PMID 39544930, 2024). "B16 melanoma cells overexpressing CCL2 enhanced Th2 cytokine production and reduced metastatic pulmonary tumor growth in wildtype C57BL/6 mice." (PMID 38928238, 2024). "Serum levels of IL-6, CXCL8 and CCL2 in particular, surge during melanoma progression, while mature NKp44+ ILC3s protect against melanoma." (PMID 38410760, 2024). "Elevated levels of CCL2 increased tumorigenicity and promoted metastasis to the lymph nodes in gastric cancer, bladder cancers and melanoma." (PMID 38809883, 2024). "IL6 has been identified as a driver of drug resistance, while increased level of CCL2 was detected in resistant melanoma cells after treatment with a BRAF inhibitor." (PMID 39175042, 2024). "Monocytes cocultured with CCL2-producing melanoma cells expressed TNF; monocyte-derived TNF induced tubule formation of HUVEC cells in vitro." (PMID 38786066, 2024). "A higher expression of CCL2, CCL3, CCL4, CXCL9 and CXCL10 transcripts was associated with more CD8+ T cell recruitment into melanoma metastases." (PMID 38928238, 2024). "Melanoma cells were found to alter the astrocyte secretion and evoke CCL2 expression and secretion, which in turn induced CCR2 expression in melanoma cells and enhanced their in vitro tumorigenic properties such as proliferation and metastasis." (PMID 37307835, 2024). "In the WM35 melanoma cell line, the CCL2 secreted by tumor cells recruited cytotoxic T lymphocytes by binding to CCR4." (PMID 38928238, 2024). "The macrophage chemoattractant CCL2 is expressed on melanoma cells and regulates macrophage function in melanoma in a concentration-dependent manner." (PMID 37398649, 2023). "Data reported in the literature have shown that WNT5A can regulate the secretion of IL-6 and CCL2 in other types of cancer, including melanoma and non–small cell lung cancer." (PMID 37607007, 2023). "Here, our analysis in YUMM3.3 melanoma showed that Ccl2 was upregulated by Activin-A both in the tumor cells and in fibroblasts." (PMID 38304252, 2023). "Previous studies in melanoma have reported that a low concentration of CCL2 promoted the survival of tumour cells, while a high concentration of CCL2 resulted in the destruction of tumour mass and high infiltration of immune cells." (PMID 37108548, 2023).
melanoma (continued). "In general, CAFs aid melanoma progression and metastasis by secreting inflammatory cytokines (e.g., CCL2, IL-6, and IL-8) and pro-angiogenic factors (e.g., VEGF), and by promoting an invasive melanoma cell phenotype." (PMID 37345186, 2023). "In their study, the authors measured high CCL2 expression levels in melanoma cells and plasma of patients after vemurafenib treatment." (PMID 36982460, 2023). "On the other hand, serum CCL2 has been poorly investigated as potential biomarker in melanoma patients." (PMID 35173725, 2022). "Our results showed that both CD4 and CD8 T cell subsets were equally capable of inhibiting melanoma-conditioned macrophage-derived CCL2, VEGF, and IL-6 in a contact-independent manner." (PMID 35265066, 2022). "In an ACT model directed against the melanosomal protein RAB38, recurrent melanomas with dedifferentiated features also showed increased myeloid cell recruitment, related to increased secretion of myeloid cell-attracting chemokines (CCL2, 3, 5)." (PMID 35432344, 2022). "Some of the cytokines produced by human melanoma cells (IL-6, IL-8, CCL5 (RANTES), CXCL1–3 (MGSA-GROa-c), and monocyte chemotactic protein-1 (MCP-1/CCL2) are associated with tumour invasiveness and aggressiveness." (PMID 35334544, 2022). "This is of particular significance for patients with BRAF-positive melanoma treated with vemurafenib, as CCL2 and myeloid cell infiltration are hallmarks of vemurafenib resistance." (PMID 35265066, 2022). "Particularly, serum levels of IL-6, CXCL8 and CCL2 have been previously shown to increase during melanoma progression." (PMID 35173725, 2022). "Blocking PARP-1, ATM, or NF-κB in melanoma cells prevents the secretion of chemokine CCL2 thereby restricting the deleterious pro-invasive properties of the inflammatory SASP mediated by PNAS." (PMID 33855023, 2021). "CCL2 has a strong link to chemotherapy and radiotherapy resistance and tumor progression in breast 39, 40, 57, prostate 38, 58-60, pancreatic 61, melanoma 62, lung 63, renal 64 and ovarian 65 cancers." (PMID 33664852, 2021). "CCL2 induces overexpression of the Cavα2δ1 subunit in the VGCCs of primary afferents and melanoma cells, as well as overexpression of CCL2 receptors (CCR2 and CCR4)." (PMID 34575835, 2021). "For example, imiquimod, a TLR7 agonist, triggers CCL2 secretion from B16-F10-resident mast cells to mobilize anti-tumor CD8α+ plasmacytoid DCs to clear B16-F10-melanomas in a IFNAR1-dependent manner." (PMID 33922465, 2021). "Melanomas inducing expansion of CCR2-expressing monocytic-MDSCs in the TME by producing CCL2, activating MDSCs through MAPK signaling." (PMID 34095111, 2021). "BRAF inhibitor-resistant melanomas induced expansion of CCR2-expressing monocytic-MDSCs in the TME by producing CCL2, activating MDSCs through MAPK signaling." (PMID 34095111, 2021). "As determined by confocal microscopy, there is high overlap between tryptase+ mast cells and hypoxic regions (pimonidazole+ cells) in murine melanomas including B16-F1 and -F10, along with overlap with CCL2 expression in the former." (PMID 33922465, 2021). "In a spontaneous transgenic mouse melanoma model, treatment with vorinostat resulted in a significant delay in disease onset, downregulation of chemokine (c-c motif) ligand 2 (CCL2) and the recruitment of MDSCs." (PMID 34149732, 2021). "The enhanced expression of CCL2 was reported in many types of cancer, including multiple myeloma, melanoma, esophageal, gastric, colorectal, lung, breast, ovary, and prostate cancer." (PMID 32019112, 2020). "The acquisition of an HIF1/NFkB-directed proinflammatory phenotype was characterized by the induced production and release of several factors, including TNFα, CCL5, IL6, VEGFA, CXCL8, PGE2 and CCL2, which had a prosurvival effect on melanoma cells." (PMID 32967672, 2020). "Conversely, down-regulation of CCL2 and/or miR-34a restores apoptosis and melanoma sensitivity to vemurafenib." (PMID 32604720, 2020).
melanoma (continued). "In vivo, CCL2 blockade by either injection of CCL2 small-interfering RNA into tumors of mice injected with Snail transfected B16-F10 murine melanoma cells or treatment with mAb resulted in decreased tumor growth and metastasis." (PMID 31921102, 2019). "The macrophage chemoattractant CCL2 is expressed on melanoma cells and its effect on macrophage function in melanoma is concentration-dependent." (PMID 30899263, 2019). "Early studies in mice showed that PLX4720 downregulated the expression of the CCL2 gene and of its protein, both in BRAF (V600E)-mutated melanoma xeno-graphs and in de novo occurring melanomas." (PMID 31762942, 2019). "In vivo, knockout of CCL2 in primary tumors of mice injected intradermally with B16-F10 (melanoma) and LLC cells (lung carcinoma) inhibited this neutrophil activation in tumor-bearing mice, and CCL2 knockout tumors showed earlier metastasis in vivo." (PMID 31921102, 2019). "In human melanomas, CCL-2, also known as MCP-1, is associated with an increased inflammatory response and recruitment of macrophages and T cells." (PMID 31134198, 2019). "Upon development of resistance to BRAF-inhibitors, human melanoma cell lines further increase their production of CCL2." (PMID 31762942, 2019). "For example, in melanoma, the upregulation of chemokine genes, such as Ccl2, Ccl3, Ccl4, Ccl5, Cxcl9, and Cxcl10, in the tumor microenvironment correlates with the influx of activated T cells into the tumor supporting the antitumor immune response." (PMID 29410666, 2018). "Considering the fact that especially melanoma cells secrete large amounts of MCP-1 (monocyte chemoattractant protein-1, also known as CCL-2) in response to TGF-β, enhanced recruitment of protumorigenic monocytes most likely contributes to immunosuppression." (PMID 30631358, 2018). "Similar data, including CCL2, has also been reported as correlating with a better prognosis for melanoma patients." (PMID 29137331, 2017). "In mice, a key chemokine for mediating monocyte recruitment to melanoma is CCL2, which signals through the receptor CCR2." (PMID 28435677, 2017). "The CCL2 expression was higher in the tumor tissues from treated patients, thus supporting an in vivo induction in melanoma cells by drug treatment." (PMID 26684239, 2016). "Inhibition of the monocyte chemoattractant protein MCP-1 (CCL2) with bindarit resulted in reduced tumor growth in human melanoma xenografts." (PMID 27886105, 2016). "When tumor samples were analyzed, the CCL2 gene expression and protein levels were higher in five melanoma lesions excised during treatment compared with the levels in two biopsies that were found to be non-tumoral at histopathology examination." (PMID 26684239, 2016). "Our results show that also melanoma patients display high CCL2 levels in the plasma, and these levels are correlated with tumor burden and LDH levels." (PMID 26684239, 2016). "CCL2 is expressed in ovarian carcinoma, cervical squamous-cell carcinoma, melanoma, and other tumors; furthermore, CCL2 is proportional to the infiltration of monocytes/macrophages." (PMID 27271610, 2016). "In conclusion, our results indicate that CCL2 and miR-125b, miR-34a and miR-100 are potential targets for overcoming the resistance to BRAFi in melanoma." (PMID 26684239, 2016). "CCL2 acted as an autocrine growth factor for melanoma cells, stimulating the proliferation and resistance to apoptosis." (PMID 26684239, 2016). "Inhibition of CCL2 and of the selected miRNAs restored both the cell apoptosis and the drug efficacy in resistant melanoma cells." (PMID 26684239, 2016). "This study shows that drug treatment induces CCL2 production in melanoma cells and that CCL2 acts as an autocrine growth factor that promotes cell survival and apoptosis resistance." (PMID 26684239, 2016). "In patients, CCL2 is detected in melanoma cells in tumors and in plasma at levels that correlate with tumor burden and lactate dehydrogenase." (PMID 26684239, 2016).